LHPP (phospholysine phosphohistidine inorganic pyrophosphate phosphatase)
Description:
Phosphatase that hydrolyzes imidodiphosphate, 3-phosphohistidine and 6-phospholysine. Has broad substrate specificity and can also hydrolyze inorganic diphosphate, but with lower efficiency (By similarity).
Synonyms: HDHD2B
Tractability: Small molecule: it has a high-quality binding pocket. PROTAC: ubiquitination databases record sites on it; its protein half-life has been measured.
Target class: Enzyme; Hydrolase
Gene: Protein-coding gene on chromosome 10 (124,461,792 to 124,617,888, forward strand). Ensembl gene ENSG00000107902.
Subcellular location: Cytoplasm; Nucleus
Subcellular location (Human Protein Atlas): Cytosol; Nuclear speckles
Pathways (Reactome):
Metabolism: Pyrophosphate hydrolysis
Gene Ontology:
Molecular function: inorganic diphosphate phosphatase activity; protein binding; protein homodimerization activity; phosphatase activity
Biological process: phosphate-containing compound metabolic process
Cellular component: cytosol; nuclear speck; nucleus; cytoplasm
Genetic constraint (gnomAD): Loss-of-function variants: 24 observed, 26.72 expected, observed/expected ratio (o/e) 0.9, 90% interval 0.65 to 1.26. The upper end of that interval is the gene's LOEUF score, 1.26, which puts it in group 5 of 6, group 1 being the genes least tolerant of losing a copy. Missense variants: 345 observed, 336.62 expected, observed/expected ratio (o/e) 1.02, 90% interval 0.94 to 1.12. Synonymous variants: 145 observed, 143.34 expected, observed/expected ratio (o/e) 1.01, 90% interval 0.88 to 1.16.
Homologues: Orthologues: chimpanzee LHPP (90% identical), rat Lhpp (90% identical), rabbit LHPP (89% identical), mouse Lhpp (88% identical), macaque LHPP (86% identical), guinea pig LHPP (86% identical), pig LHPP (81% identical), dog LHPP (76% identical), tropical clawed frog lhpp (68% identical), zebrafish lhpp (60% identical), Caenorhabditis elegans lhpp-1 (39% identical), Drosophila melanogaster CG2680 (25% identical), and 2 more. Paralogues in human: HDHD2 (42% identical), PGP (30% identical), PDXP (29% identical).
Diseases named in the same sentence as LHPP in open-access papers:
LHPP is named in the same sentence as 67 diseases in open-access papers, as found by Europe PMC text mining. Sharing a sentence is not in itself a finding about the gene and the disease. The quoted sentences say what the papers report.
hepatocellular carcinoma (17 papers, 2020 to 2025). A malignant tumor that arises from hepatocytes. "In recent years, an increasing number of studies have found that LHPP dysregulation is associated with the development of various tumors, such as oral squamous cell carcinoma, thyroid cancer, hepatocellular carcinoma, and non‐small cell lung cancer." (PMID 38292328, 2024). "Using novel monoclonal antibodies to detect pHis, we previously reported that the loss of the histidine phosphatase LHPP (phospholysine phosphohistidine inorganic pyrophosphate phosphatase) results in elevated pHis levels in hepatocellular carcinoma." (PMID 37626656, 2023). "Subsequent studies have confirmed that LHPP expression level is negatively correlated with cell cycle progression and metastasis in human HCC tissues and forced overexpression of LHPP inhibited the growth and metastasis of various human hepatoma cells." (PMID 38696452, 2024). "LHPP is a tumor suppressor gene that can play an important role in the development of hepatocellular carcinoma discovered recently." (PMID 38696452, 2024). "LHPP gained more prominence in 2018 when a study revealed its critical role in hepatocellular carcinoma and demonstrated an inverse correlation between LHPP expression levels and pHis levels." (PMID 39063217, 2024). "We previously reported that murine and human hepatocellular carcinomas (HCCs) exhibit elevated histidine phosphorylation and decreased levels of the histidine phosphatase LHPP." (PMID 37626656, 2023). "Mechanistically, as a kind of histidine phosphatase with homodimerization and diphosphatase activity, the LHPP protein is mainly correlated with substance metabolism, which has been proved in colitis, hepatocellular carcinoma and embryonic stem cells." (PMID 36376886, 2022). "The current research on LHPP in carcinoma is limited to liver carcinoma, breast carcinoma, bladder carcinoma, papillary thyroid carcinoma and pancreatic carcinoma 10-13." (PMID 35002505, 2022). "It was reported that the overexpression of LHPP in the mouse model of hepatocellular carcinoma prevented the decrease of liver function." (PMID 35002505, 2022). "The roles of phospholysine phosphohistidine inorganic pyrophosphate phosphatase (LHPP) in tumorigenesis have been recently proven in hepatocellular carcinoma (HCC), cervical, pancreatic, bladder, and thyroid cancers." (PMID 34608127, 2021). "It is recently reported that the protein histidine phosphatase LHPP is a tumor suppressor in hepatocellular carcinoma, cervical cancer, and bladder cancer." (PMID 32186702, 2020). "Recently, the anti-tumor effect of LHPP has been further demonstrated: LHPP is considered as a tumor suppressor gene of hepatocellular carcinoma by the PI3K/AKT signaling pathway, and its low expression leads to a decrease in patient survival rate." (PMID 32186702, 2020). "A previous study suggested that LHPP acted as a tumor suppressor in various cancers, such as hepatocellular carcinoma, cervical cancer, bladder cancer, pancreatic cancer, and melanoma." (PMID 33426063, 2020). "Consequently, LHPP is now considered a promising therapeutic target, and early-stage exploration has demonstrated that LHPP up-regulation with small activating RNAs reduces the proliferation and migration of hepatocellular carcinoma in a mouse model." (PMID 41124372, 2025). "In this way, utilizing known RNAa techniques to target LHPP may be a solution for hepatocellular carcinoma." (PMID 38696452, 2024). "Moreover, in patients with hepatocellular carcinoma, the low expression of LHPP is closely related with an increase in tumor malignancy and a decrease in overall survival." (PMID 35002505, 2022). "Furthermore, a recent study demonstrated that LHPP overexpression suppresses tumorigenesis in a mouse model of hepatocellular carcinoma." (PMID 36278516, 2022). "Moreover, LHPP inhibits the proliferation, migration, and invasion of hepatocellular carcinoma via decreasing the expression of MMP7, MMP9, CCNB1, and PKM2." (PMID 33426063, 2020).
hepatocellular carcinoma (continued). "In hepatocellular carcinoma (HCC), decreased expression of LHPP is positively correlated with larger tumor size and reduced overall survival." (PMID 33426063, 2020). "Several studies have shed light on the role of LHPP in inhibiting tumor growth via repression of AKT activation, evidenced in various cancers such as hepatocellular carcinoma, nasopharyngeal carcinoma, oral squamous cell carcinoma, and notably prostate cancer." (PMID 39261475, 2024). "Recently, an increasing number of publications have suggested that LHPP serves as a tumor suppressor in different tumor types, such as hepatocellular carcinoma (HCC), intrahepatic cholangiocarcinoma (ICC), glioblastoma, melanoma, cervical, bladder, thyroid, pancreatic, renal and colorectal cancers." (PMID 36376886, 2022). "LHPP, full name was Phospholysine phosphohistidine inorganic pyrophosphate phosphatase and was first reported in 2009 years and restrains human hepatocellular carcinoma (HCC) through the inhibition of PI3K/AKT signaling pathway." (PMID 33418541, 2021). "Phospholysine phosphohistidine inorganic pyrophosphate phosphatase (LHPP), a type of histidine phosphatase protein, has been proven as a tumor suppressor in hepatocellular carcinoma (HCC), cervical, pancreatic, bladder, and thyroid cancers by regulating the AKT signaling pathway." (PMID 34608127, 2021).
major depressive disorder (10 papers, 2016 to 2025). An episode of depression lasting two or more weeks without an intervening episode of mania. "A study on major depressive disorder risk shows that LHPP gene deletion in the brain or local knockout in mouse prefrontal cortex increases depression-like behaviors under chronic social defeat stress." (PMID 40406494, 2025). "An SNP in LHPP has been associated with major depressive disorder, alcohol dependence, and risky behavior." (PMID 36278516, 2022). "A genome-wide association study has revealed a single-nucleotide polymorphism (SNP) at the LHPP gene (rs35936514) correlated with major depressive disorder." (PMID 31262971, 2019). "In females from the Utah cohort, carrying 5-HT1A risk allele strengthened association of depression with the LHPP gene, a gene also identified by genome-wide association in a depressed Chinese female population." (PMID 27488351, 2016). "A single-nucleotide polymorphism at the LHPP gene (rs35936514) has been reported in genome-wide association studies to be associated with major depressive disorder (MDD)." (PMID 27843651, 2016). "As one of the only 3 known pHis phosphatases, LHPP has long been recognized as a risk gene only for major depressive disorder.In 2018, Hall and Hunter first reported that LHPP, a tumor suppressor in liver cancer, is triggered by phosphatidylinositol 3-kinase (PI3K)–AKT phosphorylation (pSer)." (PMID 40988976, 2025). "LHPP shows broad expression in the brain and could alter cellular signal transduction in patients suffering from major depressive disorder (MDD); although, its exact function has yet to be elucidated." (PMID 35342390, 2022). "For example, the CONVERGE Consortium identified two genetic associations focusing on a sample of Chinese women with recurrent severe depression: two SNPs on chromosome 10 showed evidence of association, one near the SIRT1 gene and the other in an intron of LHPP." (PMID 36231907, 2022). "LHPP or a product of a collinear brain-specific transcript, therefore, may interact with HTR1A in the pathogenesis of major depression." (PMID 27843651, 2016).
prostate carcinoma (10 papers, 2020 to 2024). A carcinoma that arises from epithelial cells of the prostate gland. "We conclude that Panobinostat’s inhibitory influence on prostate cancer growth and progression is mediated through the upregulation of LHPP, closely associated with the ferroptosis-related gene ACSL4." (PMID 39261475, 2024). "Our study validates LHPP as a genuine suppressor of prostate cancer, with its deficiency linked to an unfavorable patient outcome, thereby positing therapeutic targeting of LHPP as a potential strategy to curb prostate cancer progression and dissemination." (PMID 39261475, 2024). "Additionally, LHPP may be a crucial determinant in the Gleason score and risk assessment of prostate cancer." (PMID 39261475, 2024). "Overall, our findings indicated that the circDDX17/miR-346/LHPP pathway inhibited the progression of prostate cancer and that circDDX17 may be a new potential therapeutic or diagnostic target for treating and diagnosing prostate cancer." (PMID 32904557, 2020). "We also present substantial evidence that LHPP significantly boosts ferroptosis sensitivity in prostate cancer cells, suggesting that LHPP is a hitherto unidentified promoter of ferroptosis." (PMID 39261475, 2024). "Our study underscored the pan-HDAC inhibitor effect of Panobinostat on reversing LHPP underexpression in prostate cancer cells." (PMID 39261475, 2024). "Here, we unveil a robust correlation between reduced LHPP expression and adverse prognosis in prostate cancer." (PMID 39261475, 2024). "In summary, our research offers convincing evidence that LHPP is a promising biomarker and therapeutic target in prostate cancer." (PMID 39261475, 2024). "To clarify HDACs’ role in modulating LHPP protein levels post-Panobinostat treatment, we engineered the overexpression of different HDACs in prostate cancer cells." (PMID 39261475, 2024). "Our study elucidates a fresh perspective on the anti-prostate cancer mechanism of Panobinostat, affirming the role of LHPP as a tumor suppressor and casting light on the complex interplay of the LHPP/AKT-SKP2-ACSL4 axis in the mechanism of ferroptosis." (PMID 39261475, 2024). "In particular, the degradation of LHPP mRNA, which induces AKT phosphorylation, has been linked to the advancement of prostate cancer." (PMID 39261475, 2024). "Recent research in prostate cancer revealed that YTHDF2 induced LHPP gene alteration by directly binding to m6A-modified sites of LHPP, which supports our above findings." (PMID 36376886, 2022). "YTHDF2 has been known to mediate the mRNA degradation of NKX3.1 and LHPP in an m6A-dependent way to regulate AKT phosphorylation-induced prostate cancer progression." (PMID 34899855, 2021). "In conclusion, our study underscores LHPP as a suppressor of prostate cancer." (PMID 39261475, 2024). "To discern whether this elevation in protein levels resulted from increased mRNA synthesis or a post-translational mechanism, we conducted LHPP protein degradation half-life assays in prostate cancer cells treated with Panobinostat." (PMID 39261475, 2024). "As our study also demonstrated for the first time that LHPP might act as an anticancer gene in prostate cancer, the findings could have wide-ranging implications for the treatment of this affliction." (PMID 32904557, 2020). "Moreover, LHPP is an oncogene in colorectal, pancreatic, bladder, thyroid, and prostate cancers." (PMID 38506898, 2024). "Notably, while RGFP966 hindered the accelerated proliferation of prostate cancer cells induced by LHPP deficiency, it did not perform as effectively as Panobinostat in this regard." (PMID 39261475, 2024). "We then examined LHPP expression in various prostate cancer cell lines and found that C4-2B and DU145 cells had higher LHPP levels." (PMID 39261475, 2024). "Nonetheless, the precise manner in which LHPP affects AKT activity and, consequently, prostate cancer prognosis, remains elusive." (PMID 39261475, 2024).
prostate carcinoma (continued). "In conclusion, our findings suggest that LHPP regulates ACSL4 expression, thereby promoting ferroptosis in prostate cancer cells." (PMID 39261475, 2024). "YTHDF2 mediates the mRNA degradation of the tumor suppressors LHPP and NKX3-1 in a METTL3-dependent manner to regulate AKT phosphorylation-induced prostate cancer progression." (PMID 38281945, 2024). "A study showed that YTHDF2 can promote the degradation of PD1 mRNA in melanoma, and LHPP and NKX3-1 in prostate cancer." (PMID 34900689, 2021). "We propose a novel regulatory mechanism in which YTHDF2 mediates the mRNA degradation of the tumor suppressors LHPP and NKX3–1 in m6A-dependent way to regulate AKT phosphorylation-induced tumor progression in prostate cancer." (PMID 33121495, 2020). "In summary, we provided in vitro and in vivo evidence to elucidate that YTHDF2 mediates the mRNA degradation of the tumor suppressors LHPP and NKX3–1 in m6A-depnedent way to regulate AKT phosphorylation-induced tumor progression in prostate cancer." (PMID 33121495, 2020). "Moreover, in prostate cancer (PCa), YTHDF2 directly binds to the m6A modification sites of Phospholysine Phosphohistidine Inorganic Pyrophosphate Phosphatase (LHPP) and NK3 Homeobox 1 (NKX3-1), facilitating the degradation of mRNA and thereby reducing their expression levels within cells." (PMID 38711100, 2024).
gastric cancer (9 papers, 2022 to 2025). A primary or metastatic malignant neoplasm involving the stomach. "LHPP, downregulated in gastric cancer, can be used as an independent risk factor for gastric cancer patients, and its expression level is positively correlated with the prognosis of patients." (PMID 38292328, 2024). "Nevertheless, the specific functions and underlying mechanisms of LHPP as a tumor suppressor in gastric cancer (GC) require further exploration." (PMID 38292328, 2024). "Overall, these results indicated that LHPP has the potential to suppress tumorigenicity of gastric cancer by inhibiting invasion, metastasis, and proliferation of gastric cancer cells and reducing therapeutic resistance." (PMID 38966068, 2024). "Lin and colleagues investigated the role of LHPP in the metastasis and invasion of gastric cancer in vitro and found that knockdown of LHPP expression can induce proliferation, while upregulating the expression of reduces the proliferation ability." (PMID 38966068, 2024). "One recent study demonstrated that in gastric cancer, LHPP overexpression induces a decrease in 3-pHis labeling." (PMID 39063217, 2024). "Further experiments depicted that downregulation or knockdown of LHPP induces the abilities of gastric cancer cells to invade and migrate." (PMID 38966068, 2024). "As we have studied the function of LHPP in colorectal cancer and esophageal cancer, we selected the gastric cancer cell line HGC-27 for subsequent research." (PMID 36376886, 2022). "The low expression of LHPP was significantly related to the poor prognosis and chemotherapy sensitivity of gastric cancer patients." (PMID 35568711, 2022). "LHPP inhibits gastric cancer cells' proliferation, migration, invasion, and adhesion." (PMID 38292328, 2024). "LHPP mediated inhibition of Wnt pathway leads to the inhibition of gastric cancer cells." (PMID 38966068, 2024). "Furthermore, LHPP regulates tumor progression by inhibiting cell proliferation, migration, and invasion in gastric cancer, HCC, pancreatic cancer, renal cell carcinoma, and bladder cancer." (PMID 39063217, 2024). "In addition, we found that enhancement of LHPP expression attenuated the proliferation, migration and invasion of gastric cancer cells." (PMID 36376886, 2022). "Additionally, HGC-27 gastric cancer cells were used to evaluate the biological functions of LHPP after stable transfection with lentiviruses." (PMID 36376886, 2022). "In gastric cancer (GC), LHPP expression is downregulated in GC tissues and cells that are resistant to cisplatin." (PMID 39063217, 2024). "After that, the acetylation of LHPP can inhibit the phosphorylation of GSK3b and then inhibit the WNT pathway, so as to inhibit the glycolysis and proliferation of gastric cancer cells." (PMID 37582735, 2023). "However, a glycolysis-promoting role of METTL14 through the repression of LHPP, which inhibits cancer cell metabolism, has been reported in gastric cancer (GC)." (PMID 36859310, 2023). "Mechanistically, the m6A modification of LHPP mRNA by METTL14 represses its expression; LHPP inhibits the phosphorylation of GSK3b through acetylation and mediates HIF1A to inhibit glycolysis, proliferation, invasion and metastasis of gastric cancer cells." (PMID 35568711, 2022). "The dysregulation of LHPP expression leads to the upregulation of IGF1R, thereby activating the downstream ITGB1–FAK–SRC/YAP–c‐MYC signaling pathway, resulting in the development and progression of gastric cancer." (PMID 38292328, 2024).